PKM (pyruvate kinase M1/2)
Diseases named in the same sentence as PKM in open-access papers (continued):
Sharing a sentence is not in itself a finding about the gene and the disease.
myeloma (15 papers, 2017 to 2023). "For example, a specific AS event of PKM pre-mRNA produces PKM2, which contributes to a poor prognosis in multiple myeloma by promoting aerobic glycolysis." (PMID 35692800, 2022). "NIMA Related Kinase 2 (NEK2) promotes aerobic glycolysis through regulating splicing of Pyruvate Kinase M1/2 (PKM) and increasing the PKM2/PKM1 ratio in myeloma cells which contributes to its oncogenic activity." (PMID 31857793, 2019). "We conclude that NEK2 is a novel c-Myc target for regulation of PKM splicing and aerobic glycolysis in myeloma." (PMID 28086949, 2017). "NEK2 regulates the alternative splicing of PKM immature RNA in multiple myeloma cells by interacting with hnRNPA1/2." (PMID 28086949, 2017). "HNRNPA1/2 proteins may interact with NEK2 to regulate PKM splicing and promote aerobic glycolysis in multiple myeloma." (PMID 35897085, 2022). "We further examined whether NEK2 regulates alternative splicing of PKM pre-mRNA in NEK2 silencing myeloma cells." (PMID 28086949, 2017). "Our studies demonstrate that NEK2 promotes aerobic glycolysis through regulating splicing of PKM and increasing the PKM2/PKM1 ratio in myeloma cells which contributes to its oncogenic activity." (PMID 28086949, 2017). "Also, NEK2 has an important role in aerobic glycolysis by regulating the splicing of PKM and increasing the PKM2/PKM1 ratio in myeloma cells." (PMID 32368190, 2020). "In this study, we determine whether NEK2 increases PKM splicing and PKM2 expression resulting in high aerobic glycolysis in myeloma cells using engineered isogenic myeloma cell lines with over or lower expression of NEK2." (PMID 28086949, 2017).
thyroid cancer (14 papers, 2014 to 2026). "These DEPs were involved in cancer, including thyroid carcinoma, head and neck carcinoma, and cancer of secretory structure, in which CLU, GNAS, and PKM played an indirect role in the occurrence and development of cancer." (PMID 33299887, 2020).
atherosclerosis (13 papers, 2022 to 2025). A disease characterized by the build-up of fatty material and calcium deposition in the arterial wall resulting in partial or complete occlusion of the arterial lumen. "STAT1 has been identified as a possible therapeutic target for atherosclerosis, and PKM and PTGIS have been identified as risk markers of atherosclerosis." (PMID 39796045, 2024).
breast tumors (13 papers, 2015 to 2025). "Our study demonstrated that SNHG3/miR-330 signaling axis regulated the proliferation and metabolism of breast tumor cells through modulating PKM at the post-transcription level, providing potential therapeutic targets for inhibiting PKM in cancer treatment." (PMID 31956955, 2020). "SNHG3 functions as a miR-330-5p sponge to positively regulate PKM expression, inhibit mitochondrial oxidative phosphorylation, increase glycolysis carboxylation, and enhance breast tumor cell proliferation." (PMID 31956955, 2020). "As the expression of PKM has been reported to be regulated by various miRNA at the post-transcriptional level, we therefore investigated the effect of SNHG3/miR-330 axis on the expression of PKM and the metabolism rewiring and proliferation of breast tumor cells." (PMID 31956955, 2020). "Knockdown of CAF-secreted exosomal SNHG3 could inhibit the growth of breast tumor cells Mechanistically, SNHG3 could serve as a molecular sponge of miR-330 to regulate the expression of PKM in breast tumor cells." (PMID 31956955, 2020). "Western blot showed that increasing of miR-330 and SNHG3 knockdown significantly decreased the protein expression of PKM in breast tumor cells, while silencing of miR-330 and overexpression of SNHG3 markedly increased the PKM level in MD-MBA-453 cells." (PMID 31956955, 2020).
COVID-19 (12 papers, 2021 to 2024). A disease caused by infection with severe acute respiratory syndrome coronavirus 2. "The highest expression of PKM in COVID-19 ARDS patients is found in circulating mono-CD14+ cells." (PMID 36776845, 2023). "In module 2, mono-CD14+ cells in patients with severe COVID-19 exhibited higher expression levels of glycolysis-related genes (LDHA and PKM) and PPP-related genes (PGD and TKT), which may be involved in the proinflammatory response (upregulation of S100A8, S100A9, S100A12, and IL1B)." (PMID 33936072, 2021).
Obesity (12 papers, 2014 to 2025). Accumulation of substantial excess body fat. "However, a previous proteomics study in obesity reported decreased levels of PKM in the same tissue of individuals with obesity compared to lean controls." (PMID 38703299, 2024). "PKM may regulates gene activation in the context of inflammation and metabolic reprogramming, being a promising target for addressing some pathologies, including obesity." (PMID 38703299, 2024).
head and neck cancer (11 papers, 2014 to 2023). A primary or metastatic malignant neoplasm affecting the head and neck. "Another study suggested that highly expressed SRSF10 in head and neck cancer is also associated with aberrant PKM splicing resulting in the expression of PKM2 isoform." (PMID 36140826, 2022). "Here in this study, we report the underlying epigenetic mechanism of PKM alternative splicing in head-and-neck cancer (HNC)." (PMID 31675998, 2019). "We have investigated the largely unexplored epigenetic mechanism of PKM splicing switch in head and neck cancer (HNC) cells." (PMID 31675998, 2019). "Notably, the observed effect of curcumin on PKM splicing-switch also results in the inhibition of Warburg effect in terms of reduced glucose-uptake and lactate production and thereby reduced growth, invasion and increased apoptosis of head-and-neck cancer cells." (PMID 31675998, 2019). "Although the PKM2 overexpression is reported in HNC where it is associated with the poor prognosis, the mechanism of regulation of PKM alternative splicing has not been studied in head and neck cancer." (PMID 31675998, 2019).
heart failure (11 papers, 2016 to 2025). Inability of the heart to pump blood at an adequate rate to meet tissue metabolic requirements. "To validate the method, we first set up PRM assays for two known pyruvate kinase isozymes, namely, M1/2 (PKM1 and PKM2), which arise from MXE of PKM exons 9 and 10 and whose alternate expression regulates energy metabolism in cardiac failure." (PMID 31825849, 2019).
psoriasis (11 papers, 2021 to 2025). An autoimmune condition characterized by red, well-delineated plaques with silvery scales that are usually on the extensor surfaces and scalp. "Our preliminary search using public GEO databases indicated PKM expression is elevated in human psoriasis lesional skin." (PMID 34733164, 2021). "Using this database, our statistical analysis showed that psoriasis leision samples contained a higher level of PKM mRNA as compared to health or non leision samples." (PMID 34733164, 2021).
colorectal tumor (10 papers, 2015 to 2025). "Taken together, RhoB, HIF1A, Met, MAPK6, and PKM may play key roles in promoting colorectal tumor formation in males." (PMID 38347027, 2024). "Proteins that regulate glycolysis (PGK1, PGAM1, ENO1, PKM, TKT), ammonia detoxification (GLUD1), and other metabolic pathways (LDHA, GAPDH, MDH2) were reported to be differentially expressed in mouse xenograft colorectal tumor models with different radio- responsiveness." (PMID 38410100, 2024).
Parkinson disease (9 papers, 2014 to 2026). A progressive degenerative disorder of the central nervous system characterized by loss of dopamine producing neurons in the substantia nigra and the presence of Lewy bodies in the substantia nigra and locus coeruleus. "As the substrate of Parkin, PKM plays roles in early onset Parkinson’s disease and showed 2.2-fold higher levels in AD patients." (PMID 34367142, 2021).
pulmonary hypertension (9 papers, 2020 to 2025). Increased pressure within the pulmonary circulation due to lung or heart disorder. "Similarly, changes in splicing of PKM transcripts are well-documented in a number of disease states, with a switch from the PKM1 isoform towards the PKM2 isoform associated with pulmonary hypertension, sporadic Alzheimer’s disease, and enhancement of the Warburg effect in cancer cells." (PMID 37333180, 2023).
Cirrhosis (8 papers, 2016 to 2024). A chronic disorder of the liver in which liver tissue becomes scarred and is partially replaced by regenerative nodules and fibrotic tissue resulting in loss of liver function. "We observed an increase in PKM expression in advanced fibrosis and cirrhosis, probably due to increased HIF-1α production." (PMID 28439208, 2016).
endometrial cancer (8 papers, 2019 to 2025). Primary or metastatic malignant neoplasm involving the endometrium (mucous membrane that lines the endometrial cavity). "For diagnostic biomarker panels, MMP9 and PKM were reliable for discriminating endometrial cancer, while the combination of CTNB1, XPO2, and CAPG revealed higher performance in distinguishing endometrioid from serous endometrial cancer types." (PMID 39194522, 2024). "This study identified 28 differentially expressed proteins in endometrial cancer samples, with LDHA, PKM, MMP9, NAMPT, and SPIT1 showing the best performance in distinguishing endometrial cancer from normal tissues." (PMID 39194522, 2024).
acute myeloid leukemia (7 papers, 2019 to 2025). Acute myeloid leukemia (AML) is a group of neoplasms arising from precursor cells committed to the myeloid cell-line differentiation. "H4K5la promoted PD-L1 expression and drive immunosuppression in acute myeloid leukemia, whereas H4K12la activated the transcription of HIF1A, PKM, and LDHA, thereby promoting glycolysis and forming a positive feedback glycolysis/H4K12la/PKM2 loop in microglia." (PMID 40784455, 2025).
oral cancer (7 papers, 2019 to 2025). "Treatment with BME on oral cancer cell lines significantly reduced mRNA and protein expression levels of key glycolytic genes SLC2A1 (GLUT-1), PFKP, LDHA, PKM and PDK3." (PMID 31638999, 2019).
type 2 diabetes (7 papers, 2015 to 2024). "PKM has been reported to have important roles in many diseases including cancer and PKM polymorphisms have been shown to be associated with type 2 diabetes." (PMID 25991664, 2015). "The meaning of PKM that is involved in pathways glycolysis/gluconeogenesis, pyruvate metabolism and type II diabetes mellitus was already clarified by several studies." (PMID 27589727, 2016).
diffuse large B-cell lymphoma (6 papers, 2021 to 2025). "Results demonstrate that Aurora A, Aurora B, and the Warburg effect-related genes LDHA (lactate dehydrogenase A) and PKM (pyruvate kinase M) were significantly overexpressed in tissues obtained from patients with diffuse large B-cell lymphoma (DLBCL) as compared to normal controls." (PMID 38099309, 2023).
neuroblastoma (6 papers, 2011 to 2025). Neuroblastoma (NB) is the most common solid, extracranial childhood tumor. "Notable DSGs included PKM, which has already been shown to undergo hnRNPA1-dependent alternative splicing in neuroblastoma and MLX, encoding a MYCN transcriptional co-activator regulating glutamine metabolism genes in neuroblastoma." (PMID 39313128, 2024). "The expression of the PKM and HK2 genes strongly correlates with poor patient prognosis, suggesting that their products might confer a growth or survival advantage to neuroblastoma cells." (PMID 34847775, 2021). "Given that the expression of PKM and HK2 in neuroblastoma samples is strong predictors of negative clinical outcome, analysis of the protein content of circulating EVs could be used as a prognostic indicator and a non-invasive method for stratification of neuroblastoma patients." (PMID 34847775, 2021).
endometriosis (5 papers, 2023 to 2025). The growth of functional endometrial tissue in anatomic sites outside the uterine body. "At the same time, the relative content of pyruvate kinase M1/2 (PKM) mRNA in endometriosis biopsies of the GE and EGE groups was significantly higher than in the control group." (PMID 38612490, 2024).
nasopharyngeal carcinoma (5 papers, 2020 to 2024). A carcinoma arising from the nasopharyngeal epithelium. "Our group demonstrates TET2 delays nasopharyngeal carcinoma progression by interacting with PKM and suppressing glycolysis, suggesting that TET2 may serve as a new therapeutic target for NPC." (PMID 32774157, 2020).
pulmonary fibrosis (5 papers, 2020 to 2025). Chronic progressive interstitial lung disorder characterized by the replacement of the lung tissue by connective tissue, leading to progressive dyspnea, respiratory failure, or right heart failure. "However, elevated staining for PKM antigen was apparent in lung sections of mice treated with CP after causing BLM-induced pulmonary fibrosis." (PMID 32841217, 2020).
viral infection (5 papers, 2017 to 2025). "The timing of PKM expression time after virus infection was similar to that of Ebp1, ErbB3 (an epidermal receptor tyrosine kinase)-binding protein and also interacted with PB1 subunit of RdRp, and the elevated levels of PKM lasted until 8 hpi." (PMID 28232820, 2017). "We determined the interacting regions in both PKM2 and PA, the expression level of PKM by western blotting at different time points after viral infection, and the effects of transfection of siRNA targeting PKM on influenza virus replication." (PMID 28232820, 2017).
brain cancer (4 papers, 2018 to 2023). A primary or metastatic malignant neoplasm affecting the brain. "PKM-mediated phosphorylation of histone H3 plays a critical role in the epidermal growth factor (EGF)-induced expression of cyclin D1 and c-Myc, which further promotes tumor cell proliferation in brain cancer." (PMID 37291128, 2023).
cognitive decline (4 papers, 2025 to 2026). "First, using publicly available proteomics data, we showed that levels of PKM are increased in AD CSF in a tau-dependent manner and that these higher levels correlate with faster cognitive decline in preclinical AD patients." (PMID 40667488, 2025). "The effects we observed between higher PKM levels and faster cognitive decline in preclinical patients further supports the notion that glycolytic dysfunction occurs early in the disease process." (PMID 40667488, 2025). "First, we verified the relationship of CSF PKM levels with cognitive decline, revealing a correlation between elevated CSF PKM levels and accelerated cognitive decline in preclinical AD patients in a tau-dependent manner." (PMID 40667488, 2025). "Additionally, it was found that patients with preclinical AD and higher CSF PKM levels at baseline showed an accelerated cognitive decline over time." (PMID 40667488, 2025).
epilepsy (4 papers, 2023 to 2026). A brain disorder characterized by episodes of abnormally increased neuronal discharge resulting in transient episodes of sensory or motor neurological dysfunction, or psychic dysfunction. "Research reports that selective splicing of PKM plays an important role in epilepsy." (PMID 39428563, 2024).
fibrosis (4 papers, 2016 to 2025). the formation of excess fibrous connective tissue in an organ or tissue in a reparative or reactive process. "By slit-lamp observation, an opaque anterior lens (fibrosis) was observed in the PKM-IN-1-treated group at 3 d, but a transparent lens was observed in the Veh group, which revealed PANK4 deficiency-dependent activation of PKM2." (PMID 37196116, 2023).
Hypertension (4 papers, 2021 to 2025). The presence of chronic increased pressure in the systemic arterial system. "Among these genes, PKM and LEP were overexpressed in women older than 35 years old ( p<0.05; p<0.05); the expression of PKM, LEP, and HK2 differed remarkably in women with different BMI (all p<0.05); PKM overexpressed in women with hypertension (p<0.05)." (PMID 38166707, 2024). "Besides, women with a higher BMI tended to present higher expression of hub genes, and women with hypertension had a higher expression of PKM compared to women without." (PMID 38166707, 2024).
metastatic melanoma (4 papers, 2009 to 2023). A melanoma that has spread from its primary site to another anatomic site. "PKM2 (pyruvate kinase M1/2) expression, which controls glycolysis, has been found to be associated with tumor progression and poor survival rates in a small pilot study of metastatic melanoma patients." (PMID 38023136, 2023).
papillary thyroid carcinoma (4 papers, 2015 to 2025). "Similarly, in papillary thyroid carcinoma (PTC), the RNA-binding protein HNRNPC regulates PKM alternative splicing via m6A modification, shifting isoform expression toward PKM2 upregulation and PKM1 suppression." (PMID 40859309, 2025).
sarcoma (4 papers, 2018 to 2020). A usually aggressive malignant neoplasm of the soft tissue or bone. "HK2, GLUT1, PGK1, ENO1 and PKM were found positive correlation with SLC25A37 in sarcoma patients." (PMID 32831652, 2020). "To characterize the PKM expression patterns of sarcomas arising in KP M2+/+ and KP M2fl/fl mice, we performed Western blot analysis of PKM1 and PKM2 expression in primary tumors." (PMID 29854399, 2018). "To further characterize the PKM expression patterns of sarcomas from KP; M2+/+ and KP; M2fl/fl mice at the cell and tissue level, we performed IHC for PKM1 and PKM2." (PMID 29854399, 2018).
skin cancer (4 papers, 2015 to 2023). "Another example is the PKM-DHFR SL pair predicted for skin cancer by the SL-scan approach." (PMID 37737478, 2023).
endothelial dysfunction (3 papers, 2025). In vascular diseases, endothelial dysfunction is a systemic pathological state of the endothelium (the inner lining of blood vessels) and can be broadly defined as an imbalance between vasodilating and vasoconstricting substances produced by (or acting on) the endothelium. "Considering that PKM2 is the predominant‐expressed PKM subtype in ECs, it was speculated that PKM2 was the palmitoylated substrate protein involved in PA‐induced endothelial dysfunction." (PMID 39665133, 2025).
prostate adenocarcinoma (3 papers, 2015 to 2023). "We noticed that prostate adenocarcinoma was the only cancer type in which PKM significantly decreased compared with the normal controls, perhaps due to the slow growing nature of this cancer." (PMID 25738776, 2015).
astrocytoma (2 papers, 2013 to 2025). "To begin to examine the uniformity and relevance of PKM isoform expression and activity, we first wished to analyze PKM mRNA isoform expression in formalin-fixed or frozen normal human brain and WHO grade I–IV astrocytomas." (PMID 23451252, 2013).
chronic pancreatitis (2 papers, 2019 to 2023). A chronic inflammatory process causing damage and fibrosis of the pancreatic parenchyma. "ALDH3B1, ENO1, ALDH2, GAPDH, and LDHC had significant differences among grades, while ALDH3B1, PKM, and ALDH3B2 differed among chronic pancreatitis histories." (PMID 36814901, 2023).
gastric adenocarcinoma (2 papers, 2020 to 2021). "Normal mucosa (NM) and primary tumor (PT) of 40 metastatic gastric adenocarcinomas patients who received second-line paclitaxel-ramucirumab (PR) were analyzed for mRNA expression of the following genes: HK-1, HK-2, PKM-2, LDH-A, and GLUT-1." (PMID 32372141, 2020).
keloid (2 papers, 2020 to 2023). An irregularly shaped, elevated mark on the skin caused by deposits of excessive amounts of collagen during wound healing. "On the basis of this metabolic finding, we further revealed that PTB promotes the proliferation and migration of keloids via alternative splicing of PKM." (PMID 36982238, 2023).